IL13 (interleukin 13)
Diseases named in the same sentence as IL13 in open-access papers (continued):
Sharing a sentence is not in itself a finding about the gene and the disease.
tumor (continued). "Previous studies have shown that IL-13-PE can bind to IL-13Rα2 positive tumor cells and is highly cytotoxic to these cells in both in vitro and in vivo models of multiple malignancies 16,18,19." (PMID 25767039, 2015). "Human peripheral blood monocytes were differentiated into monocyte derived macrophages (MDM) using M-CSF and polarized into M1 by IFN-γ and LPS and into M2 macrophages by IL-4 and IL-13 or by co-culture with two different tumour cell lines." (PMID 25902944, 2015). "EAT-bearing animals treated with indomethacin showed a significant increase in IL-13 only in the 13th day of neoplasm growth." (PMID 26347589, 2015). "Exposure of TAM to tumor-derived cytokines such as IL-4, IL-10, IL-13, and M-CSF is able to convert them into polarized type II or M2 macrophages with immune-suppressive activities resulting in tumor progression." (PMID 26441986, 2015). "Treatment of animals with EAT with indomethacin promoted a significant increase in the level of IL-13 on the 13th day of neoplastic changes, coinciding with the inhibition of tumor growth." (PMID 26347589, 2015). "Type II NKT cell-induced tumor suppression can be mediated by IL-13 secretion resulting in the activation of TGF-β-secreting MDSCs that inhibit tumor-specific CD8+ T cells or type I NKT cells." (PMID 26136748, 2015). "In 10 cGy-treated F1Bx mice, plasma levels of two cytokines (G-CSF and IL-13) at the early time point and three cytokines (IP10, LIX, and RANTES) at the later time point were significantly associated with tumor latency." (PMID 25747469, 2015). "This suggests that the role of the IL-4/IL-13 axis in the pro-tumor effects of apoptosis is distinct from the IL-4Rα-dependent, alternative macrophage activation pathway." (PMID 25702581, 2015). "In our in vitro study we observed typical M1 or M2 polarization patterns in monocyte derived macrophages generated by IFN-γ/LPS or IL-4/IL-13 and a mixed M1/M2 phenotype after polarization with tumour cells." (PMID 25902944, 2015). "We have previously demonstrated that IDO expression in tumor cell lines is under the control of cytokines produced by activated T lymphocytes and that IL-13 has the capacity to repress IFN-γ-dependent induction of IDO." (PMID 24911872, 2014). "It has been established through early successful preclinical studies on first-generation CAR T cells that the IL13.E13Y zetakine (IL13 zetakine) T cells induced secretion of IFNγ, TNFα, and GM-CSF only in the presence of IL13Rα2-expressing tumor cells." (PMID 25247196, 2014). "Macrophages activated by IL-4, IL-13, and IL-10 are referred to as M2 macrophages, which can suppress inflammation, induce angiogenesis, promote tissue repair, and enhance tumor growth." (PMID 24580730, 2014). "CD4+ T cell-derived IL-4 has been reported to induce granulocyte infiltration, thereby promoting tumor clearance (an action enhanced by IL-13), and conversely increase tumor cells’ resistance to apoptosis by up-regulation of anti-apoptotic proteins." (PMID 25101088, 2014). "CARs can be designed to express either antibody to target peptide antigens on the tumor surface or ligands to target tumor-specific receptors (in this case IL13 muteins as ligands for IL13Rα2 on GBMs)." (PMID 25247196, 2014). "IL-4 and IL-13 were shown to be crucial mediators in the stimulation of invasion or immunosuppression by TAM in several tumor types." (PMID 24723924, 2014). "The cultured primary tumor cells with upregulated IL-13Rα2 were sensitive to the addition of IL-13-PE in a dose-dependent manner." (PMID 23421960, 2013). "We discovered that the tumors derived from these Tgfbr1/Pten double conditional knockout (2cKO) mice over-expressed IL-13Rα2, a high affinity receptor for IL-13 that can function as a tumor antigen." (PMID 23421960, 2013). "With confirmation of the cytotoxic effects of IL-13-PE on cultured primary murine HNSCC tumor cells, we next decided to treat Tgfbr1/Pten 2cKO mice with i.p. injections of the recombinant immunotoxin." (PMID 23421960, 2013).
tumor (continued). "Using two Tgfbr1/Pten 2cKO mice, each with multiple tumor sites, an IC50 (the concentration of drug causing 50% inhibition of protein synthesis) ranging between 45–100 ng/ml was determined for IL-13-PE." (PMID 23421960, 2013). "IL-4Rα/STAT6 signaling-dependent IL-13 produced by iNKT cells plays an important role in iNKT cell-dependent tumor immunosurveillance." (PMID 23990998, 2013). "Tumor regression was evident in the few mice that had visible tumors at the start of IL-13-PE, particularly in the SCCs around the muzzle." (PMID 23421960, 2013). "Solid tumors are frequently infiltrated by tumor-associated macrophages (TAMs), which are driven by tumor and T cell derived cytokines (especially IL-4, IL-10, and IL-13) to acquire an “alternatively activated” M2 phenotype with pro-tumor properties." (PMID 23950747, 2013). "The Tgfbr1/Pten 2cKO mice were therefore tested with IL-13-PE (50 μg/kg b.i.d. on alternate days) for two weeks starting at an early point in tumor induction when carcinomas are first beginning to appear." (PMID 23421960, 2013). "The median survival significantly increased from 69 days after tumor induction in the controls to about 92 days through IL-13-PE treatment." (PMID 23421960, 2013). "IL-13Rα2 is also an ideal target for cytotoxin-based therapy since it is a unique tumor target displaying a high affinity for IL-13 and undergoes endocytosis upon binding." (PMID 23421960, 2013). "The exact target cell that mediates the tumor protective effect upon IL-13 signaling via the IL-4Rα has yet to be defined." (PMID 24403255, 2013). "Anti-tumor activity was demonstrated with IL-13-PE in an immunodeficient xenograft mouse model using these human HNSCC cell lines and the immunotoxin treatment were well-tolerated by the mice." (PMID 23421960, 2013). "IL-13Rα1 upon interaction with the IL-4Rα binds IL-13 with high affinity and activates an intracellular signaling pathway in tumor, endothelial, fibroblast, and immune cells." (PMID 22400035, 2012). "The presence of both MDSCs and IL-13 induced type 2 macrophages has also been demonstrated to inhibit T cell function in 4T1 tumor bearing mice." (PMID 23133545, 2012). "Activation of MDSCs not only requires tumour-derived factors (e.g., tumour-derived prostaglandin E2 (PGE2)) but also IFN-γ produced by T cells and factors secreted by tumour stromal cells (like IL-1β, IL-4, IL-6, IL-10, IL-13)." (PMID 22778767, 2012). "In chronic B lymphocytic leukemia (B-CLL) models IL-13 has been shown to block apoptosis of tumor cells." (PMID 21991346, 2011). "All 7 primary tumors secreted MIF, 4 tumors secreted IL-8, 3 tumors secreted MIP-1α and only one tumor secreted IL-13 and IL12." (PMID 21647415, 2011). "A combination therapy of HDAC inhibitors and IL-13-PE demonstrated a pronounced anti-tumor effect in human tumor bearing immunodeficient mice indicating a synergistic impact on tumor response." (PMID 21477288, 2011). "IL-13-PE is highly cytotoxic to tumor cells in vitro and in vivo that express high levels of IL-13Rα2." (PMID 21477288, 2011). "Future studies will examine systemic administration of IL-13-PE in combination with HDAC inhibitors in syngenic animal tumor models." (PMID 21477288, 2011). "In some models inhibition of IL-13 or IL-13 receptors has promoted tumor growth whereas in others tumor growth has been inhibited." (PMID 21991346, 2011). "But when combined with SAHA, IL-13-PE not only decreased tumor size but also completely eliminated tumors in 66 to 83% of mice." (PMID 21477288, 2011). "In fibrosarcoma and colon carcinoma tumor models, MDSC produced TGF-β in response to IL-13 stimulation, which resulted in decreased tumor immunosurveillance of cytotoxic T-cells." (PMID 20490273, 2010). "IL-13 receptors (IL-13R) are tumor-specific, high-affinity targets that justify incorporating IL-13 into a targeted toxin as a promising strategy." (PMID 22069569, 2010).
tumor (continued). "Here, we find that the activated mast cells remodel tumor inflammatory microenvironment by upregulating CCL2, IL-10 and IL-13, which are associated with the migration and function of MDSCs, respectively." (PMID 20111717, 2010). "We observed that serum from IL13-PE-sensitized mice markedly dampened the IL13-PE-induced toxicity against target tumor cells suggesting the presence of neutralizing antibodies directed against IL13-PE in serum." (PMID 20090941, 2010). "IL13-PE cytotoxicity toward an IL-13Rα2-expressing tumor cell line in the presence of mouse sera from various groups of treated micea." (PMID 20090941, 2010). "IL13-PE was initially developed to selectively target and kill tumor cells with abnormal responses to IL-13 due to markedly up-regulated expression of IL-4R and IL-13R." (PMID 20090941, 2010). "In a model of tumor recurrence the CD8+ T cell-mediated immunosurveillance was suppressed by IL-13 producing CD1d-restricted CD4+ T cells." (PMID 19968878, 2009). "On the other hand, IL-2, IL-6, IL-8, IL-10, IFN-γ, MCP-1, MIP-1β, TNF-α and, to a lesser extent, IL-1β and IL-13 were significantly overexpressed in ER-negative tumours compared with ER-positive ones, with the greatest differences observed for IL-8 and MCP-1." (PMID 17261184, 2007). "Additionally, IL-13 induces tumor progression and enhances macrophages polarization to the M2 phenotype, favoring the immune escape of tumor cells." (PMID 40136347, 2025). "The therapeutic blockade of IL-4/IL-13 could, therefore, yield opposing outcomes, depending on tumor type and stage." (PMID 40981274, 2025). "Preclinical data suggest that IL-4 and IL-13 signaling may promote tumor progression by skewing immune responses toward a Th2 phenotype, thereby suppressing anti-tumor Th1 immunity." (PMID 40843371, 2025). "Effectively increasing the IL-13 shunt in the tumorigenic pathway may achieve a tumor promotion effect." (PMID 39758935, 2025). "In cancer, IL-13 can regulate tumor cell growth and influence immunosurveillance, with unclear data on whether IL-13 promotes or inhibits tumor progression." (PMID 40114916, 2025). "This suggests that miR-155 may regulate VEGF-mediated tumor progression through IL-13 signaling, providing further evidence of its pro-angiogenic and immune-modulatory effects in CRC." (PMID 41345725, 2025). "Moreover, Arg1 expression in TAMs is sustained by a complex tumor milieu, including IL-4/IL-13, IL-10, TGF-β, lactic acid, hypoxia, and metabolic crosstalk, which is not fully recapitulated by IL-4 alone in vitro." (PMID 41465516, 2025). "The janus kinase/signal transducers and activators of transcription signaling pathway plays a pivotal role in the polarization of M2 macrophages, mediated by cytokines such as interleukin-4 (IL-4), IL-6, and interleukin-13 (IL-13), which modulate immune responses and facilitate tumor escape." (PMID 40098971, 2025). "Within the tumor microenvironment, M2 cytokines, including IL-4, IL-13, and IL-10, are present, and TAMs in various cancer models exhibit an M2 activation profile characterized by increased expression of CD163, MRC-1, C-type lectins, IL-10, and Arg-1, as well as reduced production of IL-12." (PMID 40544275, 2025). "Conversely, in other contexts, basophils may support tumor growth by secreting cytokines such as IL-13, which reduce the proportion of Th1-like immune cells and dampen anti-tumor immunity." (PMID 41200171, 2025). "The inverse relationship between STAT1, a central mediator of IFNα-induced Th1 and pro-apoptotic signalling, and IL-13, a Th2 cytokine involved in immunoregulation and profibrotic megakaryopoiesis, suggests a shift in immune tone towards anti-tumour responses and clonal suppression." (PMID 40723157, 2025). "Notably, MC-secreted MMPs and fibrogenic cytokines, including IL13, drive fibrosis and facilitate cell migration, thereby creating conduits for invasive tumor growth and angiogenesis, key features of EMT-mediated metastasis." (PMID 40871387, 2025).
tumor (continued). "Using a xenograft SCID mice model these authors also demonstrated that CCL-2/MCP-1 is responsible for the monocyte recruitment into the tumor whereas IL-13 polarize these cells into M2 subset characterized by high expression of arginase-1 and low expression of inducible nitric oxide synthase (iNOS)." (PMID 40868818, 2025). "M1 polarization is associated with macrophage-dependent tissue damage and tumor cell killing; therefore, reduced M2 induction resulting from the blockade of IL-4 and IL-13 could improve tumor response through macrophage polarization." (PMID 40507326, 2025). "IL-13 was induced either upon co-culture with tumor cell lines, or in response to TGF-β and IL-15." (PMID 40114916, 2025). "Moreover, anti-inflammatory factors, including TGF-β, IL-10, IL-13, and Arg1 in tumor tissues were notably downregulated by sh-TBX21 injection." (PMID 41573646, 2025). "In addition, Th2 CD4+ T-cells impact the tumor immune microenvironment via the secretion of IL-4, IL-5, IL-13, and IL-17, which exert a pro-tumor growth effect." (PMID 40362529, 2025). "Regarding mechanism, IL-33 activates the p38- GATA binding protein 3 (GATA3) signaling pathway to induce M2 polarization of macrophages, promote Th2 cells and ILC2 to secrete tumor-promoting cytokines, mainly IL-4, IL-5, and IL-13, thereby playing a role in promoting tumor development." (PMID 39925809, 2025). "Conversely, upregulation of proteins involved in IL-4 and IL-13 signaling might indicate immune response modulation, possibly enhancing anti-tumor immunity or altering the tumor microenvironment." (PMID 39949745, 2025). "Previous study has demonstrated that ILC2s secrete the characteristic cytokines IL-13 and IL-4, which facilitate tumor progression by facilitating the recruitment of monocyte-derived myeloid suppressor cells (MDSCs), which plays a crucial role in suppressing anti-tumor immune responses." (PMID 38430390, 2024). "It has been reported that certain cytokines, such as interleukin-4 (IL-4), IL-5, and IL-13, secreted by Th2 cells could stimulate tumor growth." (PMID 38581008, 2024). "Produced by multiple components in the TME, IL-4 and IL-13 and their receptor systems are able to influence malignant behavior, via altering tumor proliferation, survival, and metastatic ability or suppressing tumor-directed immune surveillance mechanisms." (PMID 38726003, 2024). "However, IL-13, much more than IL-4, plays a critical role in the downregulation of tumor immunosurveillance against several types of tumors." (PMID 39057050, 2024). "Subsequently, these Th2 cells stimulate tumor development by secreting IL-4 and IL-13." (PMID 38557942, 2024). "(f) An intron variant in STAT6 (Signal Transducer And Activator Of Transcription 6), which transduces IL4 and IL13-mediated signaling, regulates the expression of genes involved in the immune response, cell survival, and tumor proliferation and metastasis, hence, it has oncogenic functions in CRC15." (PMID 39715885, 2024). "The IL-13Rα2 DNA vaccine, in combination with IL13-PE (a chimeric pseudomonas exotoxin), synergized to reduce murine breast tumor growth by multiple mechanisms, including direct tumor killing and increased T-cell tumor infiltration." (PMID 38612592, 2024). "In summary, IL-4 and IL-13 and their receptors play a significant role in tumor cell biology." (PMID 38519926, 2024). "M2a macrophages promote tumor progression through tumor-released factors and IL-4/IL-13 signaling." (PMID 39796695, 2024). "Down regulation of PCAT-1 can induce T cell recruitment and activate IL-13/IL-33 mediated pathway, inhibit tumor metastasis caused by CAF mediated activation of stromal fibroblasts, enhance the sensitivity of tumor cells to chemotherapy drugs and affect the microenvironment of tumor immune cells." (PMID 39705424, 2024).
tumor (continued). "We hypothesize that IL-13 is synergistic with IL-4 in inducing immunotherapy resistance on the one hand, and that it is the result of cytokine storms induced by tumor progression of resistance on the other." (PMID 39003253, 2024). "For instance, if the CD4 + T-cell infiltrate is indeed IL-4/IL-13 secreting, this may have functional consequences on the non-tumor cells of the TME." (PMID 38285120, 2024). "M1 macrophages express Type I cytokines with an anti-tumor effect, such as tumor necrosis factor-α (TNF-α), interferon-γ (IFN-γ), IL-6; M2 macrophages express Type II cytokines, which inhibit T cell-mediated anti-tumor response, such as IL-10, IL-13, transforming growth factor-β (TGF-β)." (PMID 39735340, 2024). "On one hand, IL-13 may exert its effects by inhibiting tumor cell apoptosis through the activation of intracellular signaling pathways when it binds to receptors on the surface of tumor cells." (PMID 39267832, 2024). "The type 1 immune cytokine IFNγ promotes macrophage polarisation towards the anti-tumour proinflammatory IL-12-producing phenotype, while stimulation by the type 2 cytokines IL-4 and IL-13 results in polarisation towards the tumour-promoting alternatively activated phenotype." (PMID 38745765, 2024). "The modulation of interleukin-4 and interleukin-13 signaling pathways could be a pivotal mechanism by which epimedium impedes tumor development." (PMID 39011503, 2024). "In this context, a prospective approach targeting IL-13 may work synergistically with current CTCL drugs with a direct anti-tumor effect." (PMID 38398754, 2024). "For example, a microbiota that favors inflammation may promote the secretion of pro-tumorigenic cytokines by MAIT cells, such as IL-17 and IL-13, contributing to tumor growth and progression." (PMID 38545100, 2024). "In cancers, inhibitors of IL-13 could enhance anti-tumor defenses, thus serving as potential cancer immune therapeutics." (PMID 38970088, 2024). "Therefore, the IL-13/PTP1B/SHN3 pathway would contribute to the immunosuppressive microenvironment, associated with chronic inflammation and tumor progression observed in GBM and other cancers." (PMID 37963919, 2023). "PD-L1, TGFB1, IL10, and IL13 are primary effectors for immunosuppressive tumor microenvironment." (PMID 36906597, 2023). "An ELISA assay revealed that HRSdx cells secreted higher amounts of molecules involved in the immunosuppressive monocyte tumor education (IL-13, TGF-β, M-CSF, L-lactate, and PGE2), stromal cell proliferation (FGF), T-cell, fibroblast, and monocyte recruitment, and prognostic markers (CCL5 and TARC)." (PMID 38067159, 2023). "TAMs at the tumor site, stimulated by different cytokines, differentiate into M1-type macrophages (pro-inflammatory phenotype) with anti-tumor effects or M2-type macrophages (anti-inflammatory phenotype) that inhibit anti-tumor effects and release IL-4, IL-10, and IL-13." (PMID 37055849, 2023). "Among them, M2 is the phenotype that exerts suppressive inflammatory overreaction and negative immunomodulatory effects, which can be polarized into M2a, M2b, M2c, and M2d subtypes when stimulated by IL-4/IL-13, LPS/immunocomplexes, IL-13/TGF-β, and tumor-associated factors, respectively." (PMID 37283946, 2023). "CCT3-mediated Th2 deviation in tumor microenvironment may link to a worse outcome for LUAD, since Th2 cytokines IL-4 IL-5, IL-9 and IL-13 trigger the differentiation of tumor-associated M2 macrophages." (PMID 36918801, 2023). "Additionally, Ad5f35 transduced macrophages did not differentiate into M2 macrophages when stimulated with IL-4, IL-10, IL-13 or a tumor-conditioned medium." (PMID 37510993, 2023). "In contrast, M2 macrophages, also known as alternatively activated, are polarized by anti-inflammatory molecules Interleukin-4 (IL-4) and Interleukin-13 (IL-13) and are characterized by supporting tumor growth angiogenesis, metastasis, and resistance to chemotherapeutics." (PMID 38116133, 2023).